RNU6-783P (RNA, U6 small nuclear 783, pseudogene)
Gene: Small nuclear RNA gene on chromosome 11 (23,849,778 to 23,849,882, forward strand). Ensembl gene ENSG00000252519.
Homologues: Orthologues: chimpanzee U6 (97% identical), macaque U6 (88% identical), guinea pig U6 (75% identical), pig U6 (75% identical). Paralogues in human: RNU6-1145P (81% identical), RNU6-1031P (79% identical), RNU6-1227P (79% identical), RNU6-38P (79% identical), RNU6-47P (79% identical), RNU6-698P (79% identical), RNU6-83P (79% identical), RNU6-116P (78% identical), RNU6-1209P (78% identical), RNU6-1307P (78% identical), RNU6-1310P (78% identical), RNU6-1316P (78% identical), and 1284 more.